BET1L (Bet1 golgi vesicular membrane trafficking protein like)
Description:
Vesicle SNARE required for targeting and fusion of retrograde transport vesicles with the Golgi complex. Required for the integrity of the Golgi complex (By similarity).
Synonyms: GS15; GOLIM3; BET1L1; HSPC197
Tractability: Antibody: UniProt predicts a signal peptide or a membrane-spanning region. PROTAC: ubiquitination databases record sites on it; its protein half-life has been measured.
Gene: Protein-coding gene on chromosome 11 (167,784 to 207,399, reverse strand). Ensembl gene ENSG00000177951.
Subcellular location: Golgi apparatus membrane; Golgi apparatus, trans- Golgi network membrane
Subcellular location (Human Protein Atlas): Golgi apparatus; Nucleoplasm
Pathways (Reactome):
Vesicle-mediated transport: COPI-mediated anterograde transport; Intra-Golgi traffic
Gene Ontology:
Molecular function: protein binding; SNAP receptor activity
Biological process: regulation of retrograde vesicle-mediated transport, Golgi to ER; retrograde transport, endosome to Golgi; membrane fusion
Cellular component: endosome; Golgi apparatus; membrane; Golgi membrane; SNARE complex; cytosol; Golgi stack
Genetic constraint (gnomAD): Loss-of-function variants: 13 observed, 12.22 expected, observed/expected ratio (o/e) 1.06, 90% interval 0.69 to 1.66. The upper end of that interval is the gene's LOEUF score, 1.66, which puts it in group 6 of 6, group 1 being the genes least tolerant of losing a copy. Missense variants: 154 observed, 154.58 expected, observed/expected ratio (o/e) 1, 90% interval 0.87 to 1.14. Synonymous variants: 60 observed, 58.17 expected, observed/expected ratio (o/e) 1.03, 90% interval 0.84 to 1.28.
Homologues: Orthologues: dog BET1L (94% identical), mouse Bet1l (91% identical), pig BET1L (91% identical), rat Bet1l (86% identical), guinea pig BET1L (86% identical), chimpanzee BET1L (81% identical), tropical clawed frog bet1l (63% identical).
Diseases named in the same sentence as BET1L in open-access papers:
BET1L is named in the same sentence as 20 diseases in open-access papers, as found by Europe PMC text mining. Sharing a sentence is not in itself a finding about the gene and the disease. The quoted sentences say what the papers report.
uterine fibroids (4 papers, 2018 to 2022). "Bet1 Golgi vesicular membrane trafficking protein-like (BET1L) rs2280543 single nucleotide polymorphism (SNP) and diet have been independently associated with uterine leiomyoma (UL)." (PMID 35477381, 2022). "In this study, BET1L rs2280543 CT + TT was associated with a lower risk of uterine fibroids, especially among vegetarians." (PMID 35477381, 2022). "BET1L, a protein receptor that regulates Golgi vesicular membrane trafficking, is associated with an increased chance of uterine fibroids." (PMID 33920951, 2021). "It has been shown that a change in a single nucleotide polymorphism of the BET1L gene is related to a lower risk of uterine fibroids in European Americans." (PMID 33920951, 2021).
adenoma (1 paper, 2025). A neoplasm arising from the epithelium. "Colocalization analysis confirmed that the association signals at BET1L and OAS1 were shared between colorectal cancer and colon polyps, supporting a common genetic basis for adenoma progression to malignancy." (PMID 40303978, 2025).
colorectal cancer (1 paper, 2025). A primary or metastatic malignant neoplasm that affects the colon or rectum. "Recent studies have demonstrated that increased expression of BET1L promotes colorectal cancer cell growth both in vitro and in vivo, and is associated with advanced tumor stages and poorer patient prognosis." (PMID 40303978, 2025). "To further investigate the pleiotropic effects of BET1L, we visualized the association signals for rs12226698 in both colorectal cancer and colon polyps using a LocusCompare plot." (PMID 40303978, 2025). "The identification of BET1L and OAS1 as novel loci associated with colorectal cancer (CRC) in East Asian populations provides significant insights into the disease’s pathogenesis." (PMID 40303978, 2025). "Collectively, these findings highlight the importance of metabolic and immune pathways in the pathogenesis of colorectal cancer and suggest that BET1L and OAS1 could serve as potential biomarkers or therapeutic targets." (PMID 40303978, 2025). "Similarly, exploring BET1L’s role in metabolic and vesicular transport pathways may uncover novel links between colorectal cancer and systemic metabolic health." (PMID 40303978, 2025). "Among these, BET1L and OAS1 were previously unreported in colorectal cancer studies, while BMP2 had been identified in European populations, highlighting both novel and shared genetic risk factors across ancestries." (PMID 40303978, 2025).
fibroids (1 paper, 2022). "Therefore, we investigated the independent and interactive effects of vegetarian diet and BET1L rs2280543 on uterine fibroids in Taiwanese women." (PMID 35477381, 2022).
glaucoma (1 paper, 2024). Increased pressure in the eyeball due to obstruction of the outflow of aqueous humor. "In this study, the SNPs with high OR values for cataract exposure on glaucoma were ZNF800 (rs62621812 with OR = 1.213), LOC338694;MYEOV (rs79721202 with OR = 1.144), BMP3 (rs72868578 with OR = 1.131), SOX2-OT (rs9823623 with OR = 1.093), and BET1L (rs11245997 with OR = 1.085)." (PMID 38674349, 2024).
intracranial aneurysm (1 paper, 2019). "A genome-wide association study (GWAS) identified that BET1L rs2280543 at chromosome 11p15.5 was a susceptibility loci of intracranial aneurysm (IA)." (PMID 31275455, 2019).
myocardial infarction (1 paper, 2025). Gross necrosis of the myocardium, as a result of interruption of the blood supply to the area, as in coronary thrombosis. "BET1L was further identified in the multi-trait analysis of CRC and myocardial infarction." (PMID 40303978, 2025).
tumor (3 papers, 2016 to 2025). "After adjustment of the data based on tumor characteristics, several genes (e.g., serpin family A member 4 (SERPINA4) and blocked early in transport 1 homolog (BET1L)) were still associated with better PFS in White patients only." (PMID 33920951, 2021).
cardiovascular diseases (1 paper, 2023). "We also considered the pleiotropic effects of BET1L, and performed a sensitivity analysis after excluding the individuals who died due to cerebrovascular and cardiovascular diseases (N = 6088)." (PMID 36737517, 2023).
colon polyps (1 paper, 2025). "We identified 25 genome-wide significant loci for CRC and colon polyps, including three novel loci in East Asian populations: BET1L (rs12226698, 11p15.5), OAS1 (rs2525858, 12q24.13), and BMP2 (rs4813802, 20p12.3)." (PMID 40303978, 2025). "Colocalization analysis confirmed strong shared association signals between BET1L and OAS1 in CRC and colon polyps, supporting their pleiotropic effects in colorectal neoplasia." (PMID 40303978, 2025). "In this analysis of CRC and colon polyps, we identified 25 genome-wide significant loci, including three novel loci in East Asian populations: rs12226698 at 11p15.5 (BET1L), rs2525858 at 12q24.13 (OAS1), and rs4813802 at 20p12.3 (BMP2)." (PMID 40303978, 2025).
BET1L also shares sentences with these, for which no sentence is quoted: Uterine leiomyoma (2 papers); ankylosing spondylitis (1); carcinoma (1); celiac disease (1); diabetes (1); Hypertension (1); infection (1); multiple sclerosis (1); myasthenia gravis (1); spinal muscular atrophy (1).